STAR (steroidogenic acute regulatory protein)
Diseases named in the same sentence as STAR in open-access papers (continued):
Sharing a sentence is not in itself a finding about the gene and the disease.
Adrenal insufficiency (12 papers, 2007 to 2026). Insufficient production of steroid hormones (primarily cortisol) by the adrenal glands. "Both missense variants (p.Arg182His and p.Arg182Cys) and nonsense variants (p.Tyr134Ter and p.Gln264Ter) resulted in severe adrenal insufficiency and female external genitalia in 46, XY individuals, indicating near‐complete loss of StAR function." (PMID 41502797, 2026). "The hormonal assay and genetic diagnosis confirmed a mutation in the StAR protein, leading to adrenal insufficiency." (PMID 39229408, 2024). "We report a novel StAR gene mutation (c.652G > A (p.Ala218Thr) in a girl with congenital adrenal insufficiency and heterochromia iridis." (PMID 31666050, 2019). "Loss of StAR function is characterized by impaired synthesis of adrenal and gonadal steroids, causing adrenal insufficiency, disorder of sex development (DSD) and in some cases failure of pubertal development." (PMID 31666050, 2019). "Case 2, with a 46,XX karyotype and unambiguous female genitalia, presented with adrenal insufficiency and hyperpigmentation, illustrating how STAR mutations in 46,XX individuals may manifest solely with adrenal symptoms, making diagnosis more challenging." (PMID 41502797, 2026). "Mutations in genes related to steroid biosynthesis (such as CYP11A1, CYP17A1, HSD3B2, HSD17B3, and StAR) will lead to androgen synthesis disorders with adrenal insufficiency besides the SRD5A2 gene mutation which results in the insufficient transformation of dihydrotestosterone from testosterone." (PMID 40247401, 2025). "While biochemical markers such as low cortisol and aldosterone levels, along with elevated ACTH and plasma renin activity, may suggest adrenal insufficiency, definitive diagnosis requires genetic confirmation through identification of mutations in the STAR gene." (PMID 41502797, 2026). "The consistent presentation of female external genitalia in 46,XY individuals, alongside early‐onset adrenal insufficiency, emphasizes the essential role of StAR in steroidogenesis and sexual differentiation." (PMID 41502797, 2026). "No other pathogenic variants were found in genes associated with skeletal dysplasias (e.g., FGFR3, COL1A1), adrenal insufficiency (e.g., NR0B1, STAR), or growth retardation (e.g., IGF1R)." (PMID 41218602, 2025). "In the future, StAR mutations (both inherited and de novo mutations) resulting in classic lipoid CAH should be considered all over the world in the differential diagnosis of newborn babies and infants with primary adrenal insufficiency." (PMID 28637490, 2017).
Infertility (11 papers, 2016 to 2023). "The changes in 110, 85, 72, 60, and 55░kDas-phosphorylated and StAR proteins found in DM testes might be associated with the suppression of spermatogenesis, resulting in male sub/infertility." (PMID 31583374, 2019). "Higher levels of the StAR (P < 0.05), aromatase (P < 0.0001) and ERβ (P < 0.01) proteins were detected in the control infertile group (group 1B) than in the eutopic infertile group (group 2B)." (PMID 31878927, 2019). "On the contrary, the variants [p.(Ser58Leu), p.(Leu75Phe), p.(Gly79Val), p.(Gly125Asn); p.(Asn126Lys); p.(Trp128Gly)] inhibited StAR activity, and the patients with these variants did not present with infertility." (PMID 33796131, 2021). "By illustrating the potential physiological role of melatonin in the regulation of StAR expression and P4 production in hGL cells, our results may serve to improve current strategies used to treat clinical infertility." (PMID 31619582, 2019). "In addition to basal and stimulated P4 production, mRNA and protein levels of key enzymes such as P450scc, StAR, and 3βHSD should be evaluated across age, BMI, pregnancy outcome, and infertility type." (PMID 28938894, 2017). "In summary, similar trends of levels of the STAR/StAR, CYP19A1/aromatase, and HSD17B1/17β-HSD1 transcripts and proteins were observed in fertile and infertile patients from both groups." (PMID 31878927, 2019). "When samples from the control infertile group (group 1B) were compared with samples from the OE infertile group (group 2B), higher levels of the NR5A1 (P < 0.0001), STAR (P < 0.0001), CYP19A (P < 0.01), ESR1 (P < 0.05) and ESR2 (P < 0.001) transcripts were detected in group 1B than in group 2B." (PMID 31878927, 2019). "Of all missense variants, the variants p.(Arg103Cys), p.(His104Pro), p.(Ser107Asn), and p.(Phe112Tyr) all failed to inhibit the StAR activity, of which the p.(Arg103Cys) mutant was consistent with the female patients manifesting infertility in the BPES type I family." (PMID 33796131, 2021).
Obesity (11 papers, 2011 to 2026). Accumulation of substantial excess body fat. "Studies have presented compelling evidence that HFD intake and obesity conspire to down-regulate the expression of StAR and P450scc, culminating in a distressing impact on reproductive function." (PMID 40264244, 2025). "In a rat model, prepubertal obesity resulted in a reduced number of Leydig cells, the decreased expressions of steroidogenic acute regulatory protein (StAR), and compromised ovarian oxidative stress and DNA repair." (PMID 40600011, 2025). "The decrease of StAR expression in our HFD-STZ model was similar to that previously found in an obesity model, in that it resulted in decreases in testosterone levels." (PMID 31583374, 2019). "In a recent study using non-human primates, weight gain directly impaired P4-secretion, which was accompanied by decreased mRNA expression for LH receptor, P450scc, STAR and 3βHSD within the CL, suggesting that obesity can directly affect CL function." (PMID 28938894, 2017). "Ensures sperm membrane integrity and sperm motility; activates GPR120/ERK signaling pathway in Leydig cells and upregulates 3β-HSDH and StAR to promote testosterone; confers host resistance to HFD-induced obesity and inflammation." (PMID 38765683, 2024). "In parallel with the decrease in testosterone levels, the expression of P450Scc, StAR, and 17βHSD genes significantly decreased and CYP19A1 expression increased in the obesity group compared to the control group (p < 0.05)." (PMID 36644444, 2023). "Other authors also demonstrated a decrease in the expression of the StAR gene in the testes of rats with T2DM and HFD-induced obesity." (PMID 35008624, 2021).
breast carcinoma (9 papers, 2017 to 2026). "Specifically, the association of StAR with ER+/PR+ breast cancer indicates that StAR acts as a tumor promoter in the most prevalent hormone sensitive breast cancer." (PMID 31060224, 2019). "Despite the regulatory events involved, the impact of StAR to serve as a risk factor in affecting the survival of ER+/PR+ breast cancer opens up a new avenue in breast cancer research." (PMID 31060224, 2019). "Additionally, TCGA breast cancer tumors associated with aberrant high expression of StAR mRNA were found to be an unfavorable risk factor for survival of patients with breast cancer." (PMID 31060224, 2019). "STAR (Steroidogenic Acute Regulatory Protein) is crucial for steroid hormone synthesis, with its increased expression promoting certain types of breast cancer." (PMID 39199284, 2024). "In a breast invasive carcinoma study (Cell 2015, 816 tumors), amplification of the StAR gene (~14%), associated with 74% ER+, 64% PR+, and 51% HER2− (15% HER2+), was found to correlate (p-value = 0.008) with poor breast cancer survival (C’)." (PMID 31060224, 2019). "Amplification of the StAR gene was observed between 12% and 26% in all breast cancer studies examined." (PMID 31060224, 2019). "Altogether, genomic analyses of key steroidogenic factors, within the context of TCGA breast cancer datasets, indicated that aberrant amplification/ expression of the StAR gene is involved, at least in part, in poor survival of ER+/PR+ breast cancer patients." (PMID 31060224, 2019). "Amplification of the StAR gene and its correlation to survival was also verified in a number of breast cancer studies." (PMID 31060224, 2019). "Further analyses of these tumors, expressing StAR mRNA, demonstrated increasing patterns of breast cancer deaths with advanced TNM stages." (PMID 31060224, 2019). "Further analyses of tumors, nodal status, and metastases of breast cancer tumors expressing StAR mRNA displayed cancer deaths in stage specific manners." (PMID 31060224, 2019). "We recently identified that StAR is a novel acetylated protein in ER+ breast cancer cells, in which three acetyl lysine residues were recognized endogenously, surmising they contribute to higher accumulation E2 in these cells." (PMID 31060224, 2019). "The analysis of Kaplan-Meier curve demonstrated that amplification of the StAR gene (~13%) was correlated with poor survival of breast cancer patients (p-value = 0.020)." (PMID 31060224, 2019). "Breast cancer tumors in TCGA datasets were predominantly ER+/PR+, in which aberrant high expression of StAR mRNA, was found to affect poor survival of breast cancer." (PMID 31060224, 2019). "By analyzing genomic profiles of StAR and steroidogenic enzyme genes for several hormone sensitive cancers, our data extend previous observations and provide novel insight that aberrant high amplification/expression of the StAR gene is correlated with poor survival of patients with breast cancer." (PMID 31060224, 2019). "Analyses of molecular genomic profiling of steroidogenic factors associated with TCGA and cBioPortal research datasets revealed that abundant amplification and/or expression of the StAR gene is connected with poor survival of patients with luminal subtype breast cancer." (PMID 31060224, 2019). "In a different category, StAR mRNA values up to 25th percentile (<9.114) as low and above 25th percentile (>9.114) as high, showed qualitatively similar effect (p = 0.034) on the survival of breast cancer." (PMID 31060224, 2019). "TCGA breast cancer tumor datasets were assessed for StAR mRNA expression." (PMID 31060224, 2019). "The involvement of StAR in breast cancer appeared specific, as translocator protein (TSPO), a mitochondrial factor involved in steroidogenesis, was not connected (TSPO gene was amplified at 0.7% with a p-value = 0.540) with cancer deaths (data not illustrated)." (PMID 31060224, 2019).
breast carcinoma (continued). "Whereas StAR and key steroidogenic enzyme genes evaluated (CYP11A1, HSD3B, CYP17A1, CYP19A1, and HSD17B) were altered to varying levels in these hormone responsive cancers, amplification of the StAR gene was correlated with poor overall survival of patients afflicted with breast cancer." (PMID 31060224, 2019). "Higher amplification of the StAR gene (~13%) was next evaluated for its impact on breast cancer." (PMID 31060224, 2019). "Kaplan-Meier curve generated with StAR mRNA values up to 50th percentile (<10.2) as low and above 50th percentile (>10.2) as high, was found to correlate with poor survival (p-value = 0.038) of patients with breast cancer." (PMID 31060224, 2019). "Additionally, accumulation of E2 mirrored StAR protein expression in both noncancerous and cancerous breast cell lines, suggesting that StAR plays a key role in the development of ER+/PR+ breast cancer." (PMID 31060224, 2019). "The absence of mutation in the StAR gene, especially in breast cancer, suggests that amplification of the StAR gene is culpable in the transport of excess cholesterol to the inner mitochondrial membrane, resulting in increased estrogen synthesis which would promote tumorigenesis." (PMID 31060224, 2019). "Similarly, the survival of breast cancer was affected (p-value = 0.045) when Kaplan-Meier curve was generated with and without (in which all tumors, excluding homozygous deletion, was included) StAR gene amplification." (PMID 31060224, 2019). "StARD3 was first found in the metastatic axillary lymph nodes of human breast cancer cells; it has a START domain and belongs to the same subfamily as StAR in the START domain protein family." (PMID 41007402, 2025). "Through differential expression analysis and mutual information, we identified seven genes (NOL4, STAR, C8G, NEIL1, SLC46A3, FRMD6, and SCARF2) that are potential biomarkers in breast cancer." (PMID 39199284, 2024). "We identified seven potential genes within breast cancer: NOL4, STAR, C8G, NEIL1, SLC46A3, FRMD6, and SCARF2." (PMID 39199284, 2024). "In this connection, it is worth noting that expression of the StAR protein has been shown to be markedly high in ER+/PR+ breast cancer, modest in TNBC, but little to none in normal mammary epithelial cells." (PMID 31060224, 2019). "Although the impact of StAR in breast cancer remains a mystery, we recently reported that StAR protein is abundantly expressed in hormone sensitive breast cancer, but not in its non-cancerous counterpart." (PMID 31060224, 2019). "The comprehensive analyses of TCGA and cBioPortal research datasets for various hormone responsive cancers demonstrate that StAR gene is amplified (associated with a positive correlation between StAR CNA and StAR mRNA levels), but not mutated, in luminal subtype breast cancer." (PMID 31060224, 2019). "This is in support of our recent report that demonstrated that StAR protein, concomitant with E2 synthesis, is markedly expressed in ER+/PR+ breast cancer, in comparison to nearly undetectable to modest StAR and E2 levels in non-cancerous mammary epithelial cells." (PMID 31060224, 2019). "While StAR’s involvement in breast malignancy remains obscure, we recently reported that both StAR protein expression and E2 synthesis are profoundly higher in ER+/PR+ breast cancer cell lines, when compared their levels with either non-cancerous mammary epithelial cells or TNBC." (PMID 31060224, 2019). "Evaluation of the median mRNA expression of genes of the amplicon in TCGA breast cancer study discloses that a few genes (GOT1L1, ADRB3, STAR and LETM2) have a very low or no expression in breast cancers." (PMID 32987805, 2020). "Most proteins are moderately to highly expressed in several breast cancer cases with at least one antibody checked, the exception being ADGRA2, ADRB3 and STAR, whose genes are also not over-expressed at the mRNA level." (PMID 32987805, 2020).
polycystic ovary syndrome (9 papers, 2014 to 2023). A disorder that manifests as multiple cysts on the ovaries. "Additionally, oxidative stress appears to also induce key steroidogenic molecules in TC, namely, CYP11A1, CYP17A1, 3-β-HSD, and StAR, favoring hyperandrogenemia." (PMID 25763405, 2014). "Insulin increases the expression of StAR but also of 17-α-hydroxylase/17,20-lyase, 3-β-hydroxysteroid dehydrogenase and aromatase, leading to the excessive production of progesterone, 17-α hydroxyprogesterone and testosterone in polycystic ovaries compared with healthy ovaries." (PMID 36009364, 2022). "Jakimiuket al studied the genetic basis of receptors in granulosa and theca cells of polycystic ovaries and reported higher mRNA expression levels of LH receptor (LHR), StAR, CYP11A1, and CYP17A1." (PMID 27769286, 2016).
adrenocortical tumor (6 papers, 2015 to 2025). "Acute activation of S1P signalling in H295R (human adrenocortical tumour) cells is postulated to lead to increased transcription of steroidogenic acute regulatory protein (STAR) and Hormone sensitive lipase (HSL) culminating in an increase in cortisol production." (PMID 32682944, 2020). "Thus, it could be reported that TCF21 is downregulated in ACC and regulates the steroidogenic factor 1 (SF-1) and StAR protein (steroidogenic acute regulatory protein) binding to the SF-1 E-box promoter in adrenocortical tumor and normal adrenal cells." (PMID 35201460, 2021). "Thus, our aim was to analyze the expression profile of four key proteins involved in the steroidogenesis cascade, namely StAR protein, CYP11B1, CYP11B2 and CYP17A1, in different types of adrenocortical tumors." (PMID 32751564, 2020).
glucocorticoid deficiency (6 papers, 2011 to 2022). "Here we report long-term follow up of a boy with PAI presenting as isolated glucocorticoid deficiency possibly due to tri-allelic inheritance of variants in STAR and CYP11A1." (PMID 35418949, 2022). "This case describes the follow up of a boy with PAI, presenting as isolated glucocorticoid deficiency with small adrenals, possibly due to tri-allelic inheritance of two STAR mutations and the rs6161 CYP11A1 variant." (PMID 35418949, 2022). "In summary, we report two novel StAR mutations found in compound heterozygote form in two related patients (sister and brother) presenting with isolated glucocorticoid deficiency." (PMID 21647419, 2011). "Based on the presence of a micropenis and the later onset of hyperpigmentation, along with failed ACTH stimulation test and XY karyotype, we suspected the diagnosis of mutations of NR0B1, CYP11A1, and STAR genes or familial glucocorticoid deficiency (FGD) (MC2R, MRAP, NNT, and AAAS)." (PMID 36407315, 2022). "StAR gene mutations causing partial loss of function manifest atypical and may be mistaken as familial glucocorticoid deficiency." (PMID 21647419, 2011). "Here, we report the results of whole-exome sequencing of 43 patients referred to us with a diagnosis of familial glucocorticoid deficiency (FGD) who were mutation negative for MC2R, MRAP, and STAR the most commonly mutated genes in FGD." (PMID 26300845, 2015). "FGD can present with salt loss suggestive of adrenal hypoplasia, and alterations in STAR and CYP11A1 resulting in partial loss of protein function may have a predominant FGD-like phenotype, with glucocorticoid deficiency without genital abnormalities in 46,XY newborns." (PMID 27485500, 2016).
adenoma (5 papers, 2013 to 2023). A neoplasm arising from the epithelium. "We demonstrate that FADS2 expression is higher in aldosterone-producing adenomas compared to nonfunctioning adenomas or nontumorous adrenocortical tissue and correlates with the expression of STAR in aldosterone- and cortisol-producing adenomas." (PMID 37478183, 2023). "Smaller adenomas and increased cortisol production were more prevalent in ACAs with high StAR expression than in those with low StAR expression." (PMID 27606678, 2016). "In our study, high expression of StAR was observed in the majority (74.2%) of cortisol-producing adenomas." (PMID 27606678, 2016). "Cytoplasmic localization of StAR immunostaining was observed in both wild-type and mutant adenoma tissues, whereas high expression was found in 75.0% (48/64) of the tumors." (PMID 27606678, 2016). "The mRNA level of the steroidogenic enzyme STAR was high in both adenomas." (PMID 36960396, 2023). "Additionally, 99% of adenomas bearing mutations in cAMP/PKA pathway-related genes (PRKACA, GNAS, or PRKAR1A) displayed high StAR expression." (PMID 27606678, 2016). "In conclusion, this study demonstrated the association between high expression of StAR and PKA activation in ACAs, which further implied that StAR immunohistochemistry could be a valuable tool for identifying cortisol-producing adenomas that activate the cAMP/PKA signaling pathway." (PMID 27606678, 2016). "Ki-67 and p27 were the markers that exhibited the highest discriminative power for differential diagnosis between carcinomas and all type of adenomas, while IGF2 and StAR were only found to be useful for differentiating between carcinomas and ACAn and between carcinomas and ACAc respectively." (PMID 23925558, 2013).
adrenal hypoplasia (5 papers, 2007 to 2023). "A novel mutation in the StAR gene was identified in a patient with severe adrenal hypoplasia and sectorial heterochromia iridis." (PMID 31666050, 2019). "For example, FGD/FGD-like conditions (MC2R, MRAP, NNT gene defects) can present with salt loss suggestive of adrenal hypoplasia, and alterations in STAR and CYP11A1 resulting in partial loss of protein function may have a predominant FGD-like phenotype (17, –, 20)." (PMID 26523528, 2016).